PLAGL1 (PLAG1 like zinc finger 1)
Diseases named in the same sentence as PLAGL1 in open-access papers (continued):
Sharing a sentence is not in itself a finding about the gene and the disease.
glioma (4 papers, 2018 to 2023). A benign or malignant brain and spinal cord tumor that arises from glial cells (astrocytes, oligodendrocytes, ependymal cells). "It was also shown that overexpression of Plagl1 abolished the neuronal commitment of non-glioma-initiating cells and caused them to become malignant." (PMID 36437415, 2023). "Consistently, a volcano plot displayed PLAGL1 as a significantly upregulated gene in mesenchymal or core-associated glioma spheres." (PMID 33392508, 2020). "To prospectively assess PLAGL1 localization in experimental tumors, we injected edge- or core-derived glioma spheres from 3 patients into immunodeficient mice." (PMID 33392508, 2020). "Mice with PLAGL1-OE glioma sphere-derived tumors exhibited significantly worse survival due to higher tumor burden, while their gene silencing groups displayed improved overall survival by lower tumor burden compared to the control group." (PMID 33392508, 2020). "To this end, we used the 2 tumor edge-derived glioma sphere models (1051E and 101027E) for lentivirus-mediated gene overexpression (PLAGL1-OE) and knockdown by shRNA (sh#1 and #2)." (PMID 33392508, 2020). "Using clonal sphere formation as a surrogate in vitro indicator of tumor initiating capacity, we found that PLAGL1-OE glioma spheres relatively increased, whereas its gene silencing reduced it with a greater inhibitory effect of sh#2 compared to sh#1." (PMID 33392508, 2020). "In the patient tumor data in TCGA, PLAGL1 mRNA expression was markedly elevated in glioblastomas compared to lower grade gliomas." (PMID 33392508, 2020). "In contrast to these findings, overexpression of PLAGL1 was found to contribute to the tumorigenesis of glioma-initiating cells and recurrent PLAGL1 fusions (most commonly with EWSR1) were found to characterize a novel subtype of supratentorial ependymoma-like tumor in pediatric patients." (PMID 36437415, 2023). "The PLAGL1-mediated signaling might be context dependent among various cancer cells, or even within gliomas." (PMID 33392508, 2020). "However, overexpression of PLAGL1 was detected in some human neoplasms such as glioma and clear cell renal cell carcinoma suggesting an oncogenic function, as well." (PMID 30214684, 2018). "qRT-PCR with 2 additional edge- and core-derived glioma sphere models (Edge- and Core-derived g1053 spheres and g0573 spheres) showed that both PLAGL1 and CD109 were higher in the core-derived, yet CD133 was up in the edge-derived, glioma spheres in vitro." (PMID 33392508, 2020).
prostate carcinoma (4 papers, 2013 to 2023). A carcinoma that arises from epithelial cells of the prostate gland. "TP73 and WT1, which were also misregulated upon PLAGL1 knockdown, were previously found to be highly methylated in prostate cancer, along with PLAGL1." (PMID 33171905, 2020). "Of 38 studies, 27 reported significantly lower expression of PLAGL1 in prostate cancer tissue relative to healthy controls." (PMID 23890537, 2013). "This included downregulation of CBLC, a ubiquitin ligase gene with hitherto unknown functions in prostate cancer, and upregulation of PLAGL1, a transcription factor with reported tumor suppressive characteristics in the prostate." (PMID 38045004, 2023). "Loss of PLAGL1 expression has been associated with progression from benign to metastatic prostate tumors via the acquisition of androgen-independence, which enables prostate cancers to grow in the absence of androgens." (PMID 23890537, 2013). "This would be consistent with the notion that methylation of JMJD2D could promote prostate cancer development through upregulation of CBLC and METTL27 as well as through downregulation of COL4A5, GLIS3, NPR1, OSR2, PLAGL1 and RSPO3." (PMID 38045004, 2023). "Overexpression of PLAGL1 induced IGF2, H19, and CDKN1C expression in a prostate cancer cell line." (PMID 26115033, 2016). "Our results suggest an overall tendency towards disruption of methylation at imprinted loci in prostate cancer tissue, and our data provide the first suggestion of disrupted imprinting patterns in cancer for four imprinted genes (DLK1, PLAGL1, SLC22A18, and TP73)." (PMID 23890537, 2013).
rhabdomyosarcoma (4 papers, 2013 to 2023). A rare aggressive malignant mesenchymal neoplasm arising from skeletal muscle. "Although PLAGL1 was initially described as a tumor-suppressor gene, recent studies have shown its oncogenic role in glioblastomas and rhabdomyosarcomas." (PMID 24260468, 2013). "However, recent studies have described an oncogenic role of PLAGL1 in glioblastomas and rhabdomyosarcomas, suggesting that PLAGL1 functions depend on the cell context." (PMID 24260468, 2013). "In the PLAGL1:FOXO1 fusion observed here, the DNA binding domain of PLAGL1 is juxtaposed to the C-terminal TAD of FOXO1, which seems quite similar to PAX3:FOXO1 rearrangements as frequently observed in alveolar rhabdomyosarcoma." (PMID 34355256, 2021).
adenoma (3 papers, 2023 to 2025). A neoplasm arising from the epithelium. "Among these, we identified Tcf12 (transcription factor 12), Plagl1 (pleomorphic adenoma gene-like 1), and other transcription factors that exhibited decreased activity levels with cardiac maturation." (PMID 39960664, 2025). "As a member of a subfamily of zinc finger proteins (ZFPs), the pleomorphic adenoma gene (PLAG) family has three members: PLAG1, PLAG-like 1 (PLAGL1) and PLAG-like 2 (PLAGL2)." (PMID 36600208, 2023).
congenital heart disease (3 papers, 2023 to 2025). A heart disease that is present at birth. "Additionaly, Plagl1 is an imprinted gene, exhibiting specific expression of the paternal allele in multiple tissues and being implicated in the pathogenesis of congenital heart disease." (PMID 39960664, 2025). "Impaired expression of Plagl1 is implicated in the formation of congenital heart diseases (CHDs) such as the atrial septum defect." (PMID 36751888, 2023). "We also showed that PLAGL1, a cardiac transcription factor, which is often mutated in congenital heart diseases (CHDs), is not expressed in Rybp-null mutant CMCs." (PMID 36751888, 2023). "On the other hand, it seems that the role of genes, such as GATA4, TBX5, NKX2-5, HOMEZ, PLAGL1, and CITED2, in heart development is significant, as numerous studies on knockout mice report that mutations in these genes are frequently associated with VSD or other congenital heart anomalies." (PMID 39466144, 2025).
glioblastoma (3 papers, 2013 to 2021). The most malignant astrocytic tumor (WHO grade IV). "Collectively, these clinical and experimental data suggested PLAGL1 is one key regulator in the edge-TICs to cause tumor core development in glioblastoma." (PMID 33392508, 2020). "Experimentally, forced PLAGL1 overexpression enhanced, while its knockdown reduced, glioblastoma edge-derived tumor growth in vivo and subsequent mouse survival, suggesting its essential role in the E-to-C-mediated glioblastoma progression." (PMID 33392508, 2020). "As expected, glioblastoma patients with higher PLAGL1 expression exhibited shorter survival in the TCGA database." (PMID 33392508, 2020). "E-to-C axis represents an ongoing lethal process in primary glioblastoma contributing to its recurrence, partly in a PLAGL1/CD109-mediated mechanism." (PMID 33392508, 2020). "Collectively, these data suggested that PLAGL1 regulates the in vitro clonality and in vivo tumor development originally derived from edge-TICs in glioblastoma." (PMID 33392508, 2020). "Specifically, we tested if PLAGL1 as a TF binds to the promoter region for the CD109 gene in glioblastoma edge-derived cells." (PMID 33392508, 2020). "Following the identification of PLAGL1 as a potential candidate regulating the E-to-C-mediated glioblastoma malignancy, we investigated the function of PLAGL1 in our glioblastoma edge-TIC models to understand if its targeting holds any translational significance." (PMID 33392508, 2020). "In glioblastoma, PLAGL1 mRNA was relatively higher in mesenchymal tumors." (PMID 33392508, 2020). "Consistently, Pearson’s correlation analysis of the 37 glioblastoma paired samples indicated a strong linear relationship between CD109 and PLAGL1 relative expression (r = 0.7, P < .05)." (PMID 33392508, 2020).
hepatoma (3 papers, 2018 to 2023). "We also determined that the regulator region of PLAGL1 (P1 promoter) is heavily methylated in the four hepatoma cell lines, and most likely this explain the low mRNA level of the PLAGL1 gene in these tumor cell lines." (PMID 30214684, 2018). "Except for PLC/PRF/5 cells, all hepatoma cell-lines exhibited an aberrant genomic profile at 6q24.2, where the PLAGL1 gene maps." (PMID 30214684, 2018). "Our investigations revealed that genomic and epigenetic changes of PLAGL1 are also present in hepatoma cell-lines." (PMID 30214684, 2018). "In fact, the tumor cell-line HepG2 presents gain of genomic material at 6q24, the lowest degree of P1 promoter methylation, and still the transcript and expression level of PLAGL1 is similarly low to that of the other hepatoma cell lines." (PMID 30214684, 2018). "The expression in situ of PLAGL1 and p21 proteins was determined by immunocytochemistry in the four hepatoma cell-lines and fibroblasts." (PMID 30214684, 2018).
Infertility (3 papers, 2016 to 2022). "Intriguingly, gain of methylation at mICRs (e.g., KCNQ1OT1, MEST, PLAGL1 and SNRPN) and loss of methylation at pICRs (e.g., H19) are frequently observed in spermatozoa from infertile human patients." (PMID 27880848, 2016).
neuroblastoma (3 papers, 2006 to 2023). Neuroblastoma (NB) is the most common solid, extracranial childhood tumor. "It has been demonstrated that Plagl1 re-expression in a neuroblastoma cell line induces several imprinted genes, including Dlk1." (PMID 18989361, 2008). "PLAGL1 is localized on chromosome 6q24-q25, a region that is frequently deleted or epigenetically modified in many solid tumors, including neuroblastoma (unpublished data)." (PMID 16989664, 2006). "Finally, PLAGL1 was identified as a candidate neuroblastoma tumor suppressor gene in the present study." (PMID 16989664, 2006). "Further literature confirms the role of PLAGL1 as a “master switch”, a TF that regulates a substantial fraction of the IGN genes and extracellular matrix (ECM) genes, and may regulate a subset of neuroblastoma signature genes." (PMID 36437415, 2023). "For some genes only circumstantial evidence for a role in neuroblastoma is present (WSB1, CDC42, PLAGL1, PRAME and TGFBR3); that we identified these genes in the present study warrants further investigations into their possible role in neuroblastoma development." (PMID 16989664, 2006).
soft tissue sarcoma (3 papers, 2013 to 2021). A malignant neoplasm arising from muscle tissue, adipose tissue, blood vessels, fibrous tissue, or other supportive tissues excluding the bones. "In soft-tissue sarcomas, CpG107 methylation status of the PLAGL1 P1 promoter was the first prognostic biomarker for both metastasis-free survival and overall survival in the US." (PMID 29610526, 2018). "A distinct entity is formed by PLAGL1 rearranged EPNs, harboring EWSR1–PLAGL1 and less commonly PLAGL1–FOXO1 or PLAGL1–EP300 fusions, which echoes molecular landscapes of soft tissue sarcomas and a group of rare mesenchymal (non-meningothelial) and glioneuronal CNS tumors with EWSR1–non-ETS fusions." (PMID 34638438, 2021).
cervical cancer (2 papers, 2021 to 2023). A primary or metastatic malignant neoplasm involving the cervix. "This was indeed confirmed by functional enrichment analyses when Plagl1 expression was associated with EMTs in human cervical cancer samples." (PMID 36751888, 2023).
clear cell renal cell carcinoma (2 papers, 2018 to 2020). "Moreover, PLAGL1 (ZAC1/LOT1) expression has been shown to be associated with disease progression and unfavorable prognosis in clear cell renal cell carcinoma." (PMID 32391054, 2020).
gestational diabetes (2 papers, 2020 to 2022). Carbohydrate intolerance first diagnosed during pregnancy. "In the mouse placenta, Plagl1 is expressed in endothelial cells of the labyrinth layer and is differentially expressed in placentas from mice with gestational diabetes compared to placentas from control mice in a sex-specific manner." (PMID 33171905, 2020). "Interestingly, maternal gestational diabetes mellitus (GDM) has been associated with defective insulin signaling within the placenta and increased vascularization, leading us to hypothesize that Plagl1 could be misexpressed in GDM placentas." (PMID 33171905, 2020).
glioneuronal tumor (2 papers, 2021 to 2025). "Gene fusions of PLAGL1 with EWSR1 have been reported exceptionally rarely in neoplasms of the CNS, including single cases of a SMARCB1-deficient atypical teratoid/rhabdoid tumor (AT/RT) and a glioneuronal tumor, not elsewhere classified (NEC)." (PMID 34355256, 2021).
hydatidiform mole (2 papers, 2020 to 2023). A gestational trophoblastic disorder characterized by marked enlargement of the chorionic villi, hyperplasia of the villous trophoblastic cells and hydropic changes. "All these abnormalities lead to over-expression of imprinted genes located in 6q24, such as PLAGL1/ZAC (pleiomorphic adenoma gene-like 1) and HYMAI (Hydatidiform mole-associated and imprinted transcript), which are the most “likely” candidate genes." (PMID 33102403, 2020).
Hyperglycemia (2 papers, 2023 to 2024). An increased concentration of glucose in the blood. "From the biochemical examination, PLAGL1 overexpression mice group showed similar body weight as other groups, significant higher fast blood glucose and lower fast blood insulin level, indicated hyperglycemia." (PMID 39365284, 2024).
Impaired glucose tolerance (2 papers, 2018 to 2024). An abnormal resistance to glucose, i.e., a reduction in the ability to maintain glucose levels in the blood stream within normal limits following oral or intravenous administration of glucose. "Of similar interest, Plagl1 or Kcnq1 dysregulation are responsible for impaired glucose tolerance associated with insulin secretion defects." (PMID 30443025, 2018). "Then we further evaluate if PLAGL1 overexpression induce impaired glucose tolerance in mice." (PMID 39365284, 2024).
intrauterine growth restriction (2 papers, 2023 to 2025). "Plagl1 was previously shown to regulate expression of Cdkn1c, Igf2, H19, and Dlk1 and to belong to a subset of IGs that control embryonic growth and differentiation, and loss of Plagl1 function resulted in intrauterine growth restriction." (PMID 36437415, 2023).
pituitary adenomas (2 papers, 2012 to 2018). "In addition, PLAGL1 has been suggested to play a role in numerous cancers, including ovarian, breast and pituitary adenomas, with somatic deletions or gains in methylation resulting in loss of expression of this tumour suppressor gene." (PMID 22723905, 2012). "Moreover, altered expression of PLAGL1, mainly reduced, was revealed in colorectal cancer and non-functioning pituitary adenoma." (PMID 30214684, 2018).
prostate tumor (2 papers, 2013 to 2023). "Moreover, the transcription factor PLAGL1 is considered to be a tumor suppressor and its downregulation in prostate tumors is possibly due to epigenetic silencing." (PMID 38045004, 2023). "Evidence was provided to support a tendency towards reduced expression in prostate tumor tissue at DLK1, PLAGL1, SLC22A18, with less conclusive expression data for WT1 and TP73." (PMID 23890537, 2013). "On the other hand, we focused on six genes (COL4A5, GLIS3, NPR1, OSR2, PLAGL1 and RSPO3) that were significantly downregulated in human prostate tumors as well as upregulated in DU145-R427 cells, suggesting that these genes might negatively interfere with prostate tumorigenesis." (PMID 38045004, 2023).
Autoimmunity (1 paper, 2024). The occurrence of an immune reaction against the organism's own cells or tissues. "However, the connection between PLAGL1 overexpression and autoimmunity remains elusive." (PMID 39365284, 2024).
colorectal cancer (1 paper, 2018). A primary or metastatic malignant neoplasm that affects the colon or rectum. "PLAGL1 is a TSG involved in the pathogenesis of several tumor types, including ovarian, gastric, pituitary and colorectal cancer." (PMID 30214684, 2018).
dysplasia (1 paper, 2025). A usually neoplastic transformation of the cell, associated with altered architectural tissue patterns. "In conclusion, these findings suggest that PLAGL1 contributes significantly to postnatal condyle development, as Plagl1 deficiency leads to subchondral bone dysplasia." (PMID 40998797, 2025).
Ewing sarcoma (1 paper, 2021). A small round cell tumor that lacks morphologic, immunohistochemical, and electron microscopic evidence of neuroectodermal differentiation. "While EWSR1 has long been known to be involved in gene fusions in Ewing sarcoma and several other tumor entities, the role of PLAGL1 in tumorigenesis is not yet fully understood." (PMID 34355256, 2021).
human papillomavirus infections (1 paper, 2025). "More than that, there is also a close link between altered methylation levels at PLAGL1/HYMAI differentially methylated regions and high-risk human papillomavirus infections." (PMID 40084057, 2025).
hypertrophic cardiomyopathy (1 paper, 2014). A condition in which the myocardium is hypertrophied without an obvious cause. "There were differences in both pathways and genes, such as the MAPK signalling pathway, the hypertrophic cardiomyopathy pathway, and the imprinted gene PLAGL1; all of which may play important roles in development of the abnormal phenotype." (PMID 25253444, 2014).
Intellectual disability (1 paper, 2021). "In humans, the expression of PLAGL1/ZAC1 is associated with reduced growth rates and intellectual disability." (PMID 34680856, 2021).
leiomyosarcoma (1 paper, 2013). An uncommon, aggressive malignant smooth muscle neoplasm, usually occurring in post-menopausal women. "This work investigated the putative clinical prognostic role of specific CpG-site methylation levels of the PLAGL1 promoter in leiomyosarcomas and undifferentiated sarcomas." (PMID 24260468, 2013).
liver cancer (1 paper, 2018). An epithelial or non-epithelial malignant neoplasm that arises from the liver. "Therefore, we wondered how genomic imbalances at the chromosome region 6q24, where PLAGL1 gene maps, would affect the transcription and expression level of this gene, and ultimately how this influences the proliferative capacity of liver cancer cells." (PMID 30214684, 2018).
lymph node metastasis (1 paper, 2023). "The protein level of PLAGL1, Ki67+ cell rate, AJCC TNM stage, distant metastasis, lymph node metastasis and pathologic stage showed prognostic value of PAAD patients in predicting their overall survival." (PMID 36600208, 2023).
melanoma (1 paper, 2015). A malignant, usually aggressive tumor composed of atypical, neoplastic melanocytes. "Last, Osteonectin (secreted protein acidic and rich in cysteine (SPARC)), which has been implicated in metastasis of melanoma to the lungs, and PlagL1 (Pleomorphic adenoma gene-like 1), a potential tumor suppressor gene, were also overexpressed in DC-tumor fusions." (PMID 26605345, 2015).